G3BP1 (G3BP stress granule assembly factor 1)
Diseases named in the same sentence as G3BP1 in open-access papers (continued):
Sharing a sentence is not in itself a finding about the gene and the disease.
infection (continued). "In this review, we summarize the pro-viral and anti-viral roles of G3BP1 during infection among different viral families." (PMID 36851663, 2023). "To study the dynamics of SG assembly and disassembly as well as assess the impact of SGs during infection, we generated G3BP1-GFP expressing A549 cells to visualize SG formation in real time." (PMID 37983241, 2023). "Although G3BP1 influences viral propagation of Flaviviridae family, different members utilize G3BP1 at different stages of infection." (PMID 36851663, 2023). "Given that G3BP1 impacts the life cycle of many viruses, it is important to distinguish what specific functional roles are played by G3BP1 at different infection stages." (PMID 36851663, 2023). "Well-studied functions of G3BP1 include participation in the innate response to infection through activation of viral nucleic acid sensors RIG-I and cGAS and as an essential component of stress granules (SGs)." (PMID 36851663, 2023). "Although G3BP1 synergizes host immune responses to fight viral invasion, some viruses require G3BP1 for efficient infection." (PMID 36851663, 2023). "G3BP1 negatively regulates Picornaviridae infection by binding the 3′ untranslated regions (3′UTRs) or Internal Ribosome Entry Site (IRES) regions of viral RNAs to inhibit viral replication." (PMID 36851663, 2023). "To test the impact of SG formation during cbVG-high infection, we generated a G3BP1 KO model that was previously shown to be required for SG formation during RSV infection." (PMID 37983241, 2023). "Further clues are obtained from identifying the strategies that viruses employ to target G3BP1—i.e., sequestration, cleavage, or degradation—and modulate its function during infection." (PMID 36851663, 2023). "Early in infection, an interaction with the HCV RNA 3′UTR causes DDX3X accumulation in SGs with IKKα, Ras GTPase-activating protein-binding protein 1 (G3BP1), and PABP, which leads to IKKα activation and downstream activation of lipogenesis." (PMID 36393867, 2022). "The formation of SGs monitored by immunostaining decreased by 50% in G3BP1-silenced cells compared with NC-treated cells, while the fluorescence signal of PEDV infection was enhanced in G3BP1-silenced cells." (PMID 35859736, 2022). "We also observed that uninfected bystander cells assembled G3BP1-positive granules, suggesting a paracrine response triggered by infection." (PMID 35098996, 2022). "Three siRNAs targeting G3BP1 were used to verify the influence of EcG3BP1 knockdown on RGNNV infection." (PMID 35935992, 2022). "In the early stage of infection, the virus factory is surrounded by the rough endoplasmic reticulum, which recruits key translation initiating factors, such as G3BP1 and Caprin-1." (PMID 34526993, 2021). "We indeed observed colocalization of DDX3X and G3BP1 in SGs after IAV–ΔNS1 infection and also after IAV–PR8 infection followed by Ars treatment." (PMID 33766561, 2021). "Our results showed that USUV infection did not induce SGs formation at 24 h p.i., and only a slight number of G3BP1 foci were detected at 48 h p.i, possibly because of its ability to generate some ROS upon infection." (PMID 33493202, 2021). "The increase in viral titers in G3BP1, RNase L KO, and U3A cells was correlated with increased accumulation of SeV proteins during the time course of infection on immunoblots probed with anti-SeV antibodies." (PMID 32295917, 2020). "In stark contrast, infection with MNV for 9h resulted in the accumulation of G3BP1 in large cytoplasmic foci localized closely to the nucleus and colocalising with an accumulation of the viral protein NS3." (PMID 31905230, 2020). "Further analysis of the G3BP1 interactome during infection clearly confirmed a shift in composition with 230 out of 377 proteins associated with G3BP1 specific to MNV infection." (PMID 31905230, 2020).
infection (continued). "Some viruses induce SG at early time points post infection but then inhibit their formation at later stages, either by inhibiting phosphorylation of eIF2α, or by cleaving SG scaffold proteins like G3BP1." (PMID 32422883, 2020). "In contrast, during MNV infection, only 5 out of 21 of the cross-core stress granules proteins displayed a high enrichment with G3BP1, namely ZC3HAV1, FXR1 and G3BP2." (PMID 31905230, 2020). "Immunofluorescence analysis revealed that SVV infection induced G3BP1 cytoplasmic foci at the early stage of infection, and then the gradual disaggregation of G3BP1 cytoplasmic foci was observed as time progressed." (PMID 33133097, 2020). "The cellular substrates PABP and G3BP1 were left largely uncleaved despite the infection taking place, also leading to higher cell viability." (PMID 31619557, 2020). "Nevertheless, at late stages of infection nsP3 promotes SG disassembly by sequestering G3BP-1 to sites of viral replication, which correlates with an increase in viral RNA levels." (PMID 31681621, 2019). "We infected the G3BP1 mutant cell line panel with SFV and fixed at 3h and 8h post infection, to investigate the impact of GFP-G3BP1 variants on spherule formation at the PM and CPV internalization, respectively." (PMID 31199850, 2019). "Nevertheless, this supported that the GFP-G3BP1 WT cells are an appropriate model for studies on G3BP1 function in infection." (PMID 31199850, 2019). "Taken together, upon infection with RNA viruses, G3BP1 increases ubiquitination of RNF125 to attenuate RNF125 expression, thereby promoting the expression of RIG-I." (PMID 31827077, 2019). "We and others have observed that the SG protein, G3BP1, localizes to the outer margins of VFs at late times post infection in a fraction of reovirus infected cells." (PMID 31216693, 2019). "Additional infection studies centered on a newly identified host target, G3BP stress granule assembly factor 1 (G3BP1), as a novel inhibitor of FMDV IRES-dependent translation, illustrating an unappreciated mechanism of suppressing FMDV replication by G3BP1." (PMID 29887867, 2018). "Evidence indicates that poliovirus (PV) proteinase 2A induces assembly of SGs early post-infection (between 2 and 4 h), which are dispersed later in the infection through the cleavage of G3BP1 by the PV 3C proteinase (3Cpro)." (PMID 27367717, 2016). "This is supported by cellular transfection and infection assays demonstrating that the FGDFN motif interacts more readily with endogenous G3BP-1." (PMID 27383630, 2016). "Later work confirmed that infection with CVB3 or EV71 also results in G3BP1 cleavage and disassembly of SGs, with similar kinetics." (PMID 27043612, 2016). "Further, a more distantly related cardiovirus, encephalomyocarditis virus (EMCV) also cleaves G3BP1 during infection of human cells." (PMID 27043612, 2016). "Expression of uncleavable G3BP1 prevents the disassembly of SGs during infection, highlighting the importance of 3C cleavage in disrupting virus-induced SGs." (PMID 27999393, 2016). "Expression of uncleavable G3BP1 prior to infection, which prevents the disassembly of virus-induced SGs, resulted in significantly increased levels of IFN-β and other cytokines, as well as decreased virus replication." (PMID 27999393, 2016). "To determine if stress granule formation due to eIF2α phosphorylation by PKR explained the requirement for PKR during VVΔE3L infection, we probed WT and eIF2α S51A cells for stress granules, using an antibody against the stress granule marker, G3BP1." (PMID 26939124, 2016). "SGs containing IGF2BP1 protein induced by MuV infection (24 h post-infection) were only reduced by ~50% in TIA-1- or G3BP1-KD cells compared with control cells, although mRNA expression was decreased to a greater extent (data not shown)." (PMID 27560627, 2016). "PV infection transiently induces SG early in infection before actively dispersing SG through cleavage of G3BP1." (PMID 26610553, 2015).
infection (continued). "In situ probes detecting the viral 5′UTR, which interrogate only the gRNA, and 3′UTR, which detect both gRNA and sfRNA, were both found to colocalize with G3BP1 during infection." (PMID 24992036, 2014). "We demonstrated that CVB3 infection induces the formation of G3BP1-SGs up to 3 hrs post-infection (pi), but active disassembly of G3BP1-SGs occurs beyond 5 hrs pi." (PMID 24260247, 2013). "For example, anti-viral SGs are formed early in PV infection, then disassembled at late stages of infection by cleavage of G3BP1 to promote viral replication." (PMID 24260247, 2013). "Our studies demonstrated that SGs were formed early during CVB3 infection; however, G3BP1-positive SGs were actively disassembled at 5 hrs post-infection, while poly(A)-positive RNA granules persisted." (PMID 24260247, 2013). "We therefore conclude that the decrease in c-Myc protein concentration resulting from IncA (aa 121-383) in HEK293 cells and most likely also from infection of Hep-2 cells with Cp. psittaci can be ascribed to the interaction between IncA and G3BP1." (PMID 21304914, 2011). "Furthermore, we show that during infection N*M210 improves virus fitness, in part, due to its ability to potently block G3BP1 foci." (PMID 41920932, 2026). "However, this has been challenged by the observation that 3Cpro, when expressed as a heterologous protein in the EMCV-Zn surrogate infection model, is unable to suppress SG formation, despite substantial G3BP1 cleavage." (PMID 40875754, 2025). "Notably, during infection, the viral-encoded MAR-degrading nsP3 also removes ADP-ribosylation from G3BP1." (PMID 41067892, 2025). "Importantly, albeit with considerably delayed kinetics, we still observe substantial cleavage of G3BP1 during CVB3–2Amut infection, consistent with continued 3Cpro activity." (PMID 40875754, 2025). "Additionally, G3Ia and G3Ib can be used to probe the immunological role of stress granules, as G3BP1-mediated stress granules are known to form in response to infection with numerous viral RNAs." (PMID 38284934, 2024). "It remains unclear whether BPIV3 infection leads to stress granules formation and whether G3BP1 plays a role in this process and in viral replication." (PMID 38690262, 2024). "The reason for G3BP1 association with viral replication complexes and the mechanism and role of SG assembly at late infection stages are not known." (PMID 36851663, 2023). "Given that G3BP1 is a well-described target for many viruses, clarifying the precise functional roles of G3BP1 during infection will not only advance the field of host-virus interaction but may also offer novel therapeutic opportunities." (PMID 36851663, 2023). "G3BP1 plays critical yet distinct roles during infection by different families of the virus." (PMID 36851663, 2023). "The enterovirus EV71 also inhibits SG via 3C‐mediated G3BP1 cleavage later in infection." (PMID 35709333, 2023). "DENV infection induces G3BP1 punctate-like structures at the early stage of infection." (PMID 36851663, 2023). "However, our results show that protein levels of ISGs such as PKR, RIG-I, MDA5 and MAVS increased at later infection times in G3BP1 KD cells." (PMID 36851680, 2023). "One way by which G3BP1 may regulate its function during infection is through post-translational modifications." (PMID 36851663, 2023). "Recent proteomic studies provided some insights into the G3BP1 interactome during infection." (PMID 36851663, 2023). "Given that the interacting partners of G3BP1 are modulated during infection to form new complexes in a virus-specific manner, different terms have been used to differentiate for these viral-induced protein complexes, including atypical SGs (EV), anti-viral SGs (IBV), or nsP3 foci (alphaviruses)." (PMID 36851663, 2023).
infection (continued). "We attribute the contradiction regarding the requirement of G3BP1 for SG formation during infection with mononegavirales to differences in the approaches used to validate the absence of SG, and staining for TIAR represents a good alternative SG marker for this purpose." (PMID 37983241, 2023). "PV and EMCV both induce SGs early in infection and inhibit them later via G3BP1 cleavage by 3C." (PMID 35709333, 2023). "To further test the hypothesis that TDRD3 may play an antiviral role during infection, particularly in the context of SGs and G3BP1, we infected HeLa cells with dsRed-expressing CVB3 at an MOI of 0.5 to generate multistep viral growth curves." (PMID 35085371, 2022). "Thus, we analyzed the presence of biotinylated proteins in G3BP1-marked structured in APEX2-GARG-1060-expressing cells after infection." (PMID 36306280, 2022). "Indeed, we show here that TDRD3 itself is cleaved by enteroviral 2Apro, similar to 3Cpro-mediated cleavage of G3BP1 that restricts SG formation over the course of infection." (PMID 35085371, 2022). "A comparison of the degree of G3BP1 expression of the OV-SY17-infected cells and OV-SY17Δ120-infected cells revealed that the expression levels of the G3BP1 protein were decreased in the OV-SY17Δ120-infected cells, which was partially reversed after infection with OV-SY17-RV120." (PMID 34287041, 2021). "Thus, in response to ORFV infection, the expression of G3BP1 was quickly increased during the early stage of infection (as early as 30 min) to induce an antiviral innate immune response." (PMID 34287041, 2021). "Moreover, infection results in a redistribution of the RNA-binding protein G3BP1 to replication complexes and remodelling of its interacting partners, allowing the avoidance from canonical stress granules." (PMID 31905230, 2020). "At later stages of EMCV infection, cleavage of G3BP1 by the EMCV protease 3C resulted in SG dissolution concomitant with a reduced IFN-β and cytokine response, which could be rescued expressing a cleavage-resistant G3BP1 mutant." (PMID 32899736, 2020). "While the CHIKV macrodomain can de-ADP-ribosylate G3BP1 and the nsP2 protease when each is overexpressed in mammalian cells or in vitro, it is unclear if these proteins are targeted by viral macrodomains during infection." (PMID 32244383, 2020). "Similarly to the results observed with CRFK cells, infection of FEA cells with FCV resulted in the cleavage of G3BP1 into a shorter form." (PMID 27147742, 2016). "However, we cannot exclude the possibility that the delayed kinetics of PKR and G3BP1 cleavage in CVB3–2Amut infection might shield a putative role of 3Cpro in countering SGs during CVB3–2Awt infection." (PMID 40875754, 2025). "To determine if the nsp1 proteins could precipitate G3BP1 in the presence of an infection, we infected MA104 cells at an MOI of 0.1 for 4 h, then independently transfected nsp1α, nsp1β, or nsp1γ mRNA, and at 24 hpi immunoprecipitated whole-cell lysates with V5-trap magnetic agarose." (PMID 40548742, 2025). "Nonetheless, given the complex and dynamic interactions between host and virus that occur during infection in vivo, it remains formally possible that the F17A mutation may have other effects on the virus independent of its altered interaction with G3BP1/2." (PMID 38492217, 2024). "However, it remains unclear whether BPIV3 infection leads to SG formation and whether G3BP1 plays a role in this process and in viral replication." (PMID 38690262, 2024). "Furthermore, the differences in the role of G3BP1 during infection—pro-viral or anti-viral—may also depend on the type and differentiation status of the cell infected." (PMID 36851663, 2023). "In addition, CoV2 but not OC43 infection causes depletion of G3BP1 and disrupts nucleocytoplasmic shuttling of TIAR, which contributes to more potent inhibition of SG formation by this virus." (PMID 36534661, 2022). "However, the level of G3BP1 quickly declined with prolongation of infection time." (PMID 34287041, 2021).
infection (continued). "Interestingly, the respective peptide of CK2 subunit, β subunits decreased in abundance in FMDV-infected cells, suggesting that FMDV may dephosphorylate G3BP1 by CK2 sequestration upon infection." (PMID 29887867, 2018). "Furthermore, we demonstrated that SGs are actively disassembled at late times during infection where G3BP1, TIA1 and HuR dissociate from SGs back into the cytoplasm, while poly-A granules persist, suggesting that G3BP1-SGs are specifically targeted while other RNA granules such as P-bodies are not." (PMID 24260247, 2013). "Further, at late stages of infection in PRV-infected PK15 and Vero cells, G3BP1, TIA1, and IE180 localized in subnuclear regions that are devoid of marginalized host chromatin, which typically corresponds with viral DNA replication compartments." (PMID 40145738, 2025). "In conclusion, the findings of our study indicate that infection with BPIV3 impedes the formation of SGs and can potentially affect the expression of host G3BP1." (PMID 38690262, 2024). "As a consequence, the dispersed eIF4A signals indicated the inability of G3BP1-ΔRGG to support SGs assembly during both WT virus and RATA mutant infections." (PMID 39638802, 2024). "Following infection with SARS-CoV-2 F17A, viral gRNA sequestration was much more pronounced within the persistent G3BP1 condensates." (PMID 38492217, 2024). "Hereto, ICC analyses were performed at 7 days post-infection for 2 well-described protein components of stress granules (SGs), namely G3BP1 (G3BP stress granule assembly factor 1) and PABPC1 (poly(A) binding protein cytoplasmic 1)." (PMID 39351233, 2024). "Next, to examine the role of G3BP1, a key SG component in apoptosis, we transfected G3BP1-specific siRNA into HeLa cells following CVB3-GFP infection or TNF-α/CHX treatment." (PMID 36864501, 2023). "Of note, CAPRIN1 interacts with ATG16L1 and G3BP1 in uninfected cells, and they are relocalized to MNV RC upon infection." (PMID 37052473, 2023). "After demonstrating that knocking out G3BP2 was also insufficient to inhibit SG formation, we developed a G3BP1 and G3BP2 dKO cell line, which successfully stopped SG from forming during RSV cbVG-high infection." (PMID 37983241, 2023). "Certain genes were down-regulated in the single G3BP1 or G3BP2 KO, which indicate SG-independent roles for these proteins during infection." (PMID 37983241, 2023). "In the ARS positive control group and the RGNNV infected group, G3BP1 and eIF3η aggregated to form SGs and were completely co-located, suggesting that RGNNV infection induced the formation of classic SGs." (PMID 35935992, 2022). "In the early stage of infection, the FDGF motif of nsP3 forms aggregates with G3BP1/2, which can regulate the conversion of the viral genome to synthesize the negative strand." (PMID 34526993, 2021). "In this study, we found that SVV induced SG formation in the early stage of infection in a PKR-eIF2α dependent manner, as demonstrated by the recruitment of marker proteins of G3BP1 and eIF4GI." (PMID 33133097, 2020). "Under infection conditions, nsP3 binds to the N-terminal NTF2-like domain of G3BP1 and recruits it to viral replication complexes." (PMID 31199850, 2019). "Foot and Mouth Disease Virus (FMDV) does not induce SG assembly despite strongly shutoff cap-dependent translation and G3BP-1 dephosphorylation at Ser-149, suggesting that FMDV infection regulates the cellular stress response." (PMID 31681621, 2019). "Upon infection, PKR expression increases but is targeted to viral replication factories (RFs) together with NP, G3BP-1, dsRNA, PKR, phosphorylated PKR, RIG-I, and MDA-5." (PMID 31681621, 2019). "Previous work has shown that infection with PV, EMCV, or Coxsackievirus B3 also results in G3BP1 cleavage and disassembly of SGs." (PMID 29887867, 2018). "G3BP1 and G3BP2 are found spread throughout the cell, and soon after infection those are localized to nsP3 containing replication complexes in SINV infections." (PMID 29375517, 2017).